STAT3 (signal transducer and activator of transcription 3)
Diseases named in the same sentence as STAT3 in open-access papers (continued):
Sharing a sentence is not in itself a finding about the gene and the disease.
cancer (continued). "Similarly, CS-IVa-Be targets cancer cells through the inhibition of IL-6R, impacting the JAK2/STAT3 phosphorylation signaling pathway." (PMID 38699644, 2024). "Analysis of the mechanisms by which SMAD7 regulates CRC cell behavior revealed that SMAD7 binds the promoter of STAT3, and the AS-induced knockdown of SMAD7 reduces STAT3 mRNA and protein expression in CRC cells, suggesting a role for SMAD7 in the control of STAT3-dependent cancer cell behavior." (PMID 39001432, 2024). "Another study indicates that administering a STAT3 inhibitor reduces CD44 expression in biliary tract cancer and may be a promising target for reducing cancer cell stemness in OC." (PMID 39766086, 2024). "Considering STAT3’s function in promoting the transcription of pro-survival genes such as Mcl-1, this approach indicates that KS18 can proficiently interfere with a principal pathway that sustains elevated Mcl-1 levels in resistant cancer cells." (PMID 39411073, 2024). "Furthermore, we explored the influence of ROP16 I/II/III on the expressions of cell cycle-related and apoptotic-related proteins, as well as STAT3 phosphorylation, to identify the signaling pathways that are regulated by ROP16 to inhibit cancer proliferation." (PMID 39174877, 2024). "Activated STAT3, AKT, and ERK are crucial for maintaining a pro-carcinogenic inflammatory microenvironment during not only initiation of malignant transformation but also cancer progression." (PMID 39738726, 2024). "Studies have reported that both STAT3 and HIF1-α can transcriptionally upregulate the expression of WTAP in some cancer cells, but we found that LPS-induced upregulation of WTAP was not affected by SC144 treatment, which inhibited the activation of STAT3 signaling by binding to IL6ST." (PMID 39007267, 2024). "Alongside STAT3, SOCS3 may interact with several other signaling pathways, affecting cancer diagnosis and prognosis." (PMID 38534772, 2024). "Collectively, our findings suggest that the NASP/ANXA2/STAT3 axis is a potential therapeutic target for improving the prognosis of patients with GBM, which has important implications for the development of more effective and precise cancer treatments." (PMID 38605477, 2024). "Targeting STAT3 has been shown to induce immunostimulatory effects in different cancer types including AML, but the role of STAT3 in AML cell susceptibility to NK cells has not been thoroughly studied." (PMID 39034990, 2024). "Furthermore, the signaling pathways activated by these agents, NF-κB, STAT3, MAPK, and Akt, are central to the progression of cancer." (PMID 38474160, 2024). "In this study, we focus on recent evidence suggesting that STAT3 and MUC1 regulate each other’s expression in cancer cells in an auto-inductive loop and found that their interaction plays a prominent role in mediating epithelial-to-mesenchymal transition (EMT) and drug resistance." (PMID 38326371, 2024). "Additionally, STAT1 and STAT6 also play a role in metabolism as STAT1, STAT3, STAT5, and STAT6 each play a role in the creation of a dynamic metabolism within cancer cells." (PMID 38464736, 2024). "Important hallmarks of cancer terms include KRAS signaling up and IL-6/JAK/STAT3 signaling." (PMID 38627442, 2024). "Due to the reciprocal nature of this BCL3/STAT3 axis, in cancers where both BCL3 and JAK/STAT3 signaling are upregulated, combination therapies targeting both might be beneficial." (PMID 38195591, 2024). "This research offers a thorough comprehension of a complex process by which IFNγ triggers a non-canonical signaling cascade that involves STAT3 and c-Myc, leading to the manifestation of a unique metabolic phenotype of cancer cells." (PMID 38791327, 2024). "Comparing doxycycline treated (DOX + ) to untreated cells (DOX-), we observed significant increases in several signaling pathways known to impact cancer cell proliferation and survival, including increased phosphorylation of AKT1/2/3 at T308, STAT3 S727, and p70 S6 kinase, to name a few." (PMID 38182652, 2024).
cancer (continued). "ROS play a role in cancer suppression, but it has been shown that autophagy promotes tumor angiogenesis by activating the JAK2/STAT3 pathway and targeting VEGF; in addition, autophagy regulates the ability of cancer stem cells (CSCs) to differentiate into TECs." (PMID 38824197, 2024). "Brassinin prevents STAT3 signaling by modulating PIAS3, leading to reduced cancer growth (b)." (PMID 38590645, 2024). "A study demonstrated that the Lin-28B/let-7/HMGA2 axis was activated by STAT3/nuclear factor kappa B (STAT3/NFKB) to regulate the EMT/cancer stem cell formation; of note, HMGA2 plays a major role in this axis." (PMID 38361784, 2024). "STAT3 and STAT5A/B can promote cancer development, whereas STAT1 is a cancer suppressor." (PMID 38318160, 2024). "STAT3 expression was induced by v-SRC, a typical oncogenic signalling molecule known to activate STAT347, suggesting that STAT3 is involved in the regulation of PRMT5 expression in cancer cells." (PMID 38760429, 2024). "To elucidate the contribution of STAT3 in SPOP depletion-induced cancer progression, we knocked down STAT3 in 5637 cells lacking SPOP." (PMID 39479456, 2024). "Several STAT3 inhibitors have been advanced into clinical trials with promising therapeutic potential as monotherapy or in combination with other treatment modalities in HCC and other cancers." (PMID 38981878, 2024). "Similar to siRNA, ASO target genes are involved in cancer differentiation, growth, proliferation, and survival, such as Bcl-2, survivin, EGFR, signal transducer and activator of transcription 3 (STAT3), and PD-L1." (PMID 39407665, 2024). "The treatment of cancer cells with DBMSCs in the IC setting modulated the expression of various factors with a specific role in cellular adhesion, including AKT1, CALD1, CDH1, FN1, and STAT3." (PMID 39768220, 2024). "The involvement of STAT family proteins in tumorigenesis and cancer progression has been widely reported, particularly for STAT3 and STAT5, which are constitutively activated in many cancer cells and have been experimentally shown to be important in cancer progression." (PMID 38760429, 2024). "It is reported that MDSCs activate STAT3 signaling by stimulating the expression of colony stimulating factor 2 (CSF2) in epithelial ovarian cancer, thereby enhancing the transcription of SOX2, NANOG, OCT4a, C-MYC, and KLF4, as well as cancer stemness." (PMID 38561775, 2024). "Although STAT3 has been a target for developing cancer therapy for a while, STAT3 inhibitors have not been successful in the clinic." (PMID 38326371, 2024). "The phosphorylation of STAT3 by JAK at the tyrosine residue leads to STAT3 dimerization and nuclear translocation and target gene transcription (i.e., intestinal inflammation and cancer)." (PMID 38279309, 2024). "BCL3 has been recognized for some time to be a direct transcriptional target of STAT3 in a cancer context yet the reciprocal relationship was not described until relatively recently." (PMID 38195591, 2024). "Previously published researches have demonstrated that CXCR4 was overexpressed in GC and affects the proliferation, migration and invasion of cancer cells via the activation of diverse signaling pathways, such as ERK/Akt, NF-kB, JAK2/STAT3, and Wnt/β-catenin pathways." (PMID 38402299, 2024). "In addition, leptin and adipocyte-derived IL-6 enhance the expression of lysyl hydroxylase (PLOD2) by activating the JAK/STAT3 and PI3K/AKT signaling pathways, ultimately facilitating cancer cell metastasis." (PMID 39192979, 2024). "To determine the main source of OPN in vivo and validate STAT3-dependency, we analysed OPN gene expression across MAFs (GFP+), cancer cells (Epcam+), immune cells (CD45+), isolated by flow cytometry-based cell sorting from metastasis bearing Pdgfrb-GFP mice treated with STAT3i." (PMID 38678021, 2024).
cancer (continued). "This combinatorial approach aimed to block the IAPs that are overexpressed in cancer, mitigate BV6-induced side effects, and suppress STAT3 expression, which has been shown in vitro to induce anticancer responses in breast cancer, colorectal cancer, and melanoma cell lines." (PMID 39065565, 2024). "Targeting STAT3 with Resveratrol, for example, blocks the downstream effects of IL6 and has shown potential in overcoming therapy-induced resistance in OC and various other cancers." (PMID 39766086, 2024). "Similarly, several effector molecules, including CALD1, CDH1, FN1, FZD7, RAC1, STAT3, and WNT11, were downregulated in cancer cells treated with DBMSCs." (PMID 39768220, 2024). "We and others have shown, both in MPM and in other cancers, that modulation of the number and activity of chemoresistant ALDHbright cells in CRC may be mediated by IL-6-stimulated STAT3." (PMID 38791392, 2024). "These pathways include but are not limited to HIF-1α/VEGF/VEGFR2/PI3K/AKT, Wnt/β-catenin, JNK1/STAT3, and MAPK/AP-1, which may provide some new active ingredients or targets for future cancer treatment." (PMID 38611849, 2024). "Ultimately, treating HepG2 cancer cells with Pitavastatin affected significant activation of caspase-3 accompanied by down-regulation of cellular apoptotic biomarkers such as IDO, TDO, STAT3, P21, P27, IL-6, and AhR." (PMID 38653790, 2024). "On these bases, we aimed to develop an 18F-labeled molecular imaging probe for in vivo PET imaging of STAT3 in cancers because there has been no research on STAT3 imaging probes." (PMID 38834900, 2024). "STAT3 is a member of the STAT protein family, which is involved in many cellular processes, including inflammation regulation, immune response, apoptosis, early embryonic development, and cancer." (PMID 39734345, 2024). "Recently, non-canonical STAT3 signaling pathways have gained much attention due to their potential roles in cancer." (PMID 38245798, 2024). "The experimental STAT3 inhibitor WP1066 has demonstrated preclinical and clinical efficacy through inhibition of phosphorylation of STAT3, reducing target gene transcription and inducing apoptosis in cancer cells." (PMID 39456642, 2024). "The compound’s ability to target and disrupt key molecular pathways involved in cancer progression, such as the PI3K/AKT/mTOR, NF-κB, STAT3, and MAPK signaling pathways, highlights its efficacy in suppressing cancer cell proliferation, promoting apoptosis, and inhibiting metastasis." (PMID 39769996, 2024). "IL-6, as an essential trigger of epithelial-to-mesenchymal transition, activates STAT3, followed by transcription of ZEB1 and production of mesenchymal-like proteins and a mesenchymal phenotype, which is utilized by carcinoma cells to promote invasion, angiogenesis, metastasis, and apoptosis." (PMID 38541074, 2024). "A crosstalk between the STAT3 and NOTCH pathways in cancer cells has been reported." (PMID 38090567, 2023). "Compound 11c with two six-carbon chain lengths showed the highest activity, which inhibited cancer cell growth in a dose-dependent manner and could be a potential JAK/STAT3 pathway inhibitor at a relatively low concentration." (PMID 37103357, 2023). "Notably, the first-in-class antisense oligonucleotide (ASO) targeting STAT3 AZD9150 has chemical stability and anti-tumor activity in several cancers." (PMID 38164743, 2023). "The results showed that RS was closely related to KRAS signaling up, EMT and other pathways related to cancer development and metastasis, and the immune-related pathways IL6 JAK STAT3 signaling and IL2 STAT5 signaling were significantly different in patients with high and low RS." (PMID 37773804, 2023). "In addition, it can activate Src, focal adhesion kinase FAK, STAT3, JAK2/STAT3/Snail (in cancer cells), signaling kinases correlated with cancer progression." (PMID 36835413, 2023).
cancer (continued). "Deletion of IL‐6 from cancer cells also reduced Il‐6 mRNA expression in m.qu., iWAT, and gWAT of CHXIL6KO mice and resulted in a drastic reduction of plasma IL‐6 concentrations (−94%) as well as p‐STAT3 (Tyr705) levels in iWAT (−60%) and m.qu." (PMID 36351437, 2023). "STAT3 and ERK play a key role in cancer cell proliferation and migration." (PMID 37828429, 2023). "It has been well documented that STAT3 plays an oncogenic role in HCC, stimulating growth, anti-apoptosis, migration, invasion, angiogenesis, cancer stem cell properties, and immune suppression of cancer cells." (PMID 38322013, 2023). "Aberrant levels of proteins conferring resistance to TRAIL in a variety of cancer cells rely at least in part on the activation of anti-apoptotic signal transduction pathways, such as mitogen-activated protein kinase (MAPK), NF-κB, and STAT3." (PMID 38068921, 2023). "Numerous studies have indicated that STAT3 plays a key role in promoting oncogenesis and it is considered a potential therapeutic target for cancer treatment; however, there are no reports on STAT3 using pan-cancer analysis." (PMID 36977736, 2023). "We have recently discussed that STAT3 may interact with NFE2L2, and their interaction may result in a synergic or antagonistic effect with respect to cancer cell survival." (PMID 37511362, 2023). "In addition, STAT3 and STAT5 proteins are key driving factors of HPV-induced malignant tumors and play important roles in the development of a series of HPV-related cancers." (PMID 37504269, 2023). "Indeed, in our latest study, we found that STAT3 also drives Pol I-directed transcription by activating RPA34 expression, and both STAT3 and Pol I transcription-specific inhibitors can suppress cancer cell proliferation (manuscript accepted)." (PMID 36656267, 2023). "The pro-tumorigenic role of STAT3 in CRC and other cancers is well-established." (PMID 37884500, 2023). "Many inhibitors of STAT3, including BP1-102, STX-0119, and HJC0123, have been identified clinically and shown to have pro-apoptotic and antitumor activities against STAT3-overactivated cancer cells." (PMID 37183207, 2023). "The increased JAK1 and STAT3 corporately contributed to the activation of the p-STAT3 signaling pathway and further upregulated downstream effectors expressions, including VEGFA and CCND1, which finally resulted in enhanced cancer cell proliferation and metastasis in vitro and in vivo." (PMID 38001065, 2023). "Primary reports showed some specific miRNAs that affected STAT3 and ATG12 targets, while further studies demonstrated broader roles of autophagy-related microRNAs in cancer cells, showing numerous miRNAs acting at the levels of induction, nucleation, expansion, fusion, degradation, and recycling." (PMID 38132441, 2023). "In addition, UA downregulated NF-κB and STAT3 phosphorylation levels after activating SIRT1, and these two pathways play a key role in regulating cancer cachexia." (PMID 37190306, 2023). "In ICT resistance, it is believed that hyperactivated STAT3, both in cancer cells and stromal cells, may lead to ICT resistance through various mechanisms of cancer immunity suppression, as reviewed earlier." (PMID 37454231, 2023). "Activation of STAT3 could significantly increase the expression of the metastasis-related proteins MMP-2 and MMP-9 in cancer cells." (PMID 37049904, 2023). "Subsequently, co-immunoprecipitation assays were undertaken to ascertain whether PRMT6 could physically bind to STAT3, and the results disclosed a substantive interaction between PRMT6 and STAT3 in MCF-7 and MDA-MB-468 cancer cells." (PMID 37813837, 2023).
cancer (continued). "The main effect of Centipeda minima on cancer cell lines is the targeting of the Skp1-Cullin1-F-box protein (SCF) E3 ubiquitin ligase and transcription signal transducer and activator of transcription 3 (STAT3)." (PMID 38202691, 2023). "In addition, the relation between HSP90 and activation of STAT3, STAT5 and STAT6 have been reported in preclinical cancer studies, further supporting our findings." (PMID 38274815, 2023). "Besides the well-known targets such as the inhibition of the mTOR signaling pathway, several additional metformin and phenformin targets (e.g., mGPDH, ATF3, STAT3, GSK3, cyclins) have been identified in other cancers." (PMID 38146457, 2023). "Melanoma CSCs can educate neutrophils to support cancer progression in several ways, such as neutrophil recruitment via TGF-β, IL6, and IL8, enhancing N2-polarization by the activation of ERK, STAT3, and P38 pathways, as well as the overexpression of CXCR2 and NF-kB." (PMID 36672697, 2023). "According to the KEGG analysis, CHST11 may participate in PD‐L1 expression and PD‐1 checkpoint pathway in cancer by regulating genes TICAM2, LAT, TLR2, CD4, STAT3, NFKBIE and CD3D." (PMID 36062845, 2023). "Dysregulated miR-197 in various cancers received sophisticated regulatory: IL-6 appeared to stimulate and increase the levels of p-SATA3 and STAT3 protein, which inhibited the expression of miR-197 and thus contributed to oncogenesis via promoting cell proliferation, preventing apoptosis." (PMID 35913675, 2023). "The activation of STAT3 would also lead to various STAT3-dependent pathways, such as the interleukin-8/STAT3 (IL-8/STAT3) and EGFR/STAT3/SRY-box transcription factor 2 (EGFR/STAT3/SOX2) pathways, which have been shown to play important roles in cancer stemness." (PMID 37760799, 2023). "FLLL32 has exceptional biochemical properties, and in particular inhibits signal transducer and activator of transcription 3 (STAT3) phosphorylation, DNA-binding activity, and transactivation, and demonstrates significant growth suppressive activity in a variety of human cancer cells." (PMID 38027032, 2023). "Therefore, the results show that UA alleviates cancer cachexia and prevents muscle wasting by activating SIRT1 and inhibiting NF-κB and STAT3." (PMID 37190306, 2023). "Transwell assays further bolstered our observations, showing that PRMT6 enhancement distinctly amplified the migration and invasion capabilities of cancer cells with STAT3 WT, yet failed to manifest this effect in cells with STAT3 R729K mutant." (PMID 37813837, 2023). "After treated with Ro5-3335, a RUNX1-CBFβ interaction inhibitor, the phosphorylation level of EGFR (Tyr1068), STAT3 (Tyr705) and AKT (Ser473, Thr308) were significantly decreased in control cancer cell lines (SKOV3, OVCAR3) and generated the similar pattern that RUNX1 knockdown induced." (PMID 38057816, 2023). "By downregulating the combined molecular targets, such as c-MET, STAT3, and AKT and their phosphorylated forms, the activation and overexpression of cancer stem cell-like cells is suppressed along with drug resistance signaling, hence improving the overall survival of the patients." (PMID 37373393, 2023). "Moreover, blocking of IL-6 increased NK cytotoxicity to HCC cells through the inhibited expression of STAT3 and HIF-1α in cancer cells." (PMID 37501379, 2023). "In the context of our current study, demonstrating the roles of Y705-STAT3 phosphorylation in protection against CSC enrichment and EMT, it is worth noting the connection of STAT3 to the maintenance of an epithelial phenotype in cancer cells." (PMID 37190183, 2023). "To overcome these limitations, we previously developed a strategy to deliver oligonucleotide-based STAT3 inhibitors, such as antisense oligonucleotides (ASOs), specifically into Toll-like receptor-9 (TLR9) expressing myeloid cells, B cells, and certain cancer cells." (PMID 38259453, 2023).